SLC26A4-AS1 (SLC26A4 antisense RNA 1)
Gene: Long non-coding RNA gene on chromosome 7 (107,650,260 to 107,662,204, reverse strand). Ensembl gene ENSG00000233705.
Diseases named in the same sentence as SLC26A4-AS1 in open-access papers:
SLC26A4-AS1 is named in the same sentence as 1 disease in open-access papers, as found by Europe PMC text mining. Sharing a sentence is not in itself a finding about the gene and the disease. The quoted sentences say what the papers report.
myocardial infarction (1 paper, 2022). Gross necrosis of the myocardium, as a result of interruption of the blood supply to the area, as in coronary thrombosis. "To name a few, we can refer to the promoter of CDKN1A antisense DNA damage-activated RNA (PANDAR), SLC26A4 antisense RNA 1 (SLC26A4-AS1), and myocardial infarction-associated transcript (MIAT)." (PMID 35804851, 2022).